AGT (angiotensinogen)
Diseases named in the same sentence as AGT in open-access papers (continued):
Sharing a sentence is not in itself a finding about the gene and the disease.
Hypertension (continued). "The present study also pointed out the possible role of methylation pattern and its interaction with SNPs in the promoter region of AGT in the causation of hypertension." (PMID 28361007, 2017). "In the present study, we have done genotype and haplotype analysis of AGT gene in reference to hypertension to confirm the association of the two in an Indian population." (PMID 28361007, 2017). "All these studies laid foundation and make AGT gene a perfect marker to study its haplotype association with the pathogenesis of hypertension." (PMID 28361007, 2017). "In the present study, 6.61 fold risk of rs11568020, 2.339 fold risk of rs5050, 1.587 fold risk of rs4762 (in additive and Dominant model) and 2.303 fold risk of rs699 with the occurrence of hypertension suggests the role of AGT gene in hypertension." (PMID 28361007, 2017). "Renin activates angiotensinogen into angiotensin I, and ACE can split angiotensin I into active angiotensin II, which can cause vasoconstriction and lead to high blood pressure." (PMID 29137154, 2017). "Studies of patients with ADPKD also echoed the potential link between urine angiotensinogen excretion and factors associated with progression, such as hypertension, eGFR and total kidney volume." (PMID 27499720, 2016). "In univariate analysis, higher urinary AGT/Cr was associated with reduced eGFR as well as old age, hypertension, low initial eGFR, low plasma hemoglobin, high serum uric acid, large htTKV, and microalbuminuria." (PMID 26092580, 2015). "For hypertension association, AGT gene haplotype (T174M, M235T, G-6A, A-20C, G-152A, and G-217A) had been reported to interact with I/D of the ACE gene." (PMID 25961019, 2015). "We found that high urinary level of AGT/Cr was associated with lower eGFR, larger htTKV, and hypertension." (PMID 26092580, 2015). "As a novel biomarker that reflects intrarenal RAS activity, urinary AGT has been reported to be associated with hypertension, proteinuria, and renal dysfunction." (PMID 26092580, 2015). "AGT, ACE, and AT1R genes have overall effects with susceptibility to hypertension, where the SNPs of ACE have a mainly hypertension-associated effect and show an interacting effect to SNPs of AGT and AT1R genes." (PMID 25961019, 2015). "In this study, urinary AGT/Cr demonstrated a better association with concurrent eGFR, htTKV, and hypertension compared to other biomarkers including urinary NAG/Cr and β2MG/Cr." (PMID 26092580, 2015). "Other studies have also reported familial tendency of hypertension in Korean women; furthermore, association between AA genotype of angiotensinogen gene and high blood pressure (BP) leads to hypertensive disorders in pregnancy." (PMID 25530769, 2014). "Among the identified major molecular variants of AGT, M235T and T174 M variants had a significant association with hypertension." (PMID 24860821, 2014). "The activation of RAS causes retention of sodium and water by angiotensinogen and leads to the development of hypertension." (PMID 25045660, 2014). "Our study showed a higher OR 2.62 (95% CI, 1.24–5.76; P = 0.006) compared to a recent meta-analysis in Han Chinese population which reports high association between AGT M235T polymorphism and hypertension (OR = 1.54; 95% CI, 1.16–2.03; P = 0.002)." (PMID 24860821, 2014). "In Korean females, familial tendency of hypertension and angiotensinogen AA genotype had an association with high BP in hypertensive disorder during pregnancy." (PMID 25530769, 2014). "HSD11B1 overexpression in mice has been associated with dose-dependent hypertension and AGT expression in liver." (PMID 24658007, 2014). "In these cases, it is recommended that the arterial blood pressure should be monitored, and all the possible causes of hypertension during pregnancy should be tested, including genetic analysis of M235T variant of the angiotensinogen gene." (PMID 25530769, 2014).
Hypertension (continued). "Instead, M235T genotype was associated with a stepwise increase in angiotensinogen levels in white subjects and a corresponding increase in risk of hypertension in both White and Asian subjects." (PMID 24860821, 2014). "For example, chimpanzees and humans share hypertension susceptibility alleles in at least two genes: angiotensinogen (AGT) and the epithelial sodium channel γ subunit (ENaCγ), genes involved in the regulation of sodium and blood pressure homeostasis." (PMID 24485020, 2014). "AGT carries two variants: a promoter A-6G variant and the T235M variant, which are associated with hypertension." (PMID 24485020, 2014). "For evaluation of genotype effect on the risk of hypertension, four SNPs were chosen: two SNPs (AGT and ACE) related to renin-angiotensin-aldosterone system and other two SNPs (ADM and CACNB2) newly identified in genome-wide association studies." (PMID 25313554, 2014). "In summary, the genotype distributions of the AGT M235T polymorphism influenced the risk of essential hypertension in south Indian women and ACE DD is a risk in south Indian male population." (PMID 24860821, 2014). "Two different meta-analyses in Chinese populations have also confirmed that T allele of AGT M235T polymorphism is associated with essential hypertension." (PMID 24860821, 2014). "This is the first report to evaluate the simultaneous association of ACE, AGTR1, and AGT gene polymorphisms in essential hypertension by haplotype based analyses and gender specific association in south India." (PMID 24860821, 2014). "For instance, the A-6G and A-20C polymorphisms in the promoter region of AGT gene are associated, respectively, to decreased and increased risks of hypertension." (PMID 24065925, 2013). "Several studies have shown an association between angiotensinogen (AGT) promoter polymorphisms and hypertension." (PMID 24065925, 2013). "Angiotensinogen, an essential member in the rennin-angiotensin system, is responsible for hypertension, and angiotensinogen is also associated with liver cirrhosis, portal hypertension and hepatic ischemia/reperfusion injury." (PMID 23844114, 2013). "Further, there is strong evidence implicating different AGT molecular variants as the cause of human essential hypertension and organ damage during aging." (PMID 23874995, 2013). "Single nucleotide polymorphisms (SNPs) in the AGT gene, some of which are known to be significantly associated with essential hypertension and higher rates of AGT gene transcription, have been shown to associate with more rapid progression of IPF." (PMID 22500179, 2012). "Numerous studies in Chinese populations have evaluated the association between the A-6G and A-20C polymorphisms in the promoter region of angiotensinogen gene and hypertension." (PMID 22216295, 2011). "Our meta-analysis indicated significant association between angiotensinogen promoter polymorphisms and hypertension in the Chinese populations, especially in Han Chinese." (PMID 22216295, 2011). "The human T235 allelic variant of the AGT gene is associated with enhanced hepatic AGT mRNA synthesis, higher serum AGT levels, and consequent hypertension." (PMID 20613959, 2010). "Several mutations at the angiotensinogen (AGT) gene have also been studied as candidates in essential hypertension or myocardial infarction (MI)." (PMID 18637188, 2008). "On the other hand, two studies of German populations reported that the AGT T allele was a risk factor for hypertension in individuals younger than 50 years of age." (PMID 15642127, 2005). "The present study examines how polymorphisms of the insertion/deletion (I/D) ACE and M235T AGT genes account for presence and severity of hypertension, and embeds the data in a meta-analysis of relevant studies." (PMID 15642127, 2005).
Hypertension (continued). "An exclusively AGT-dependent hypertension is thus theoretically impossible, although two exceptional cases of hypertension associated with hepatic cell tumors producing large amounts of AGT have been reported." (PMID 15811183, 2005). "The ACE I/D polymorphism does not contribute to the presence and severity of essential hypertension, while the AGT M235T TT genotype confers a significantly decreased risk for the development of hypertension in the population studied here." (PMID 15642127, 2005). "The M235T variant of the AGT is significantly associated with essential hypertension whereas the genotype TT or allele T is a possible genetic marker or risk factor for hypertension in Malaysian subjects." (PMID 15811183, 2005). "The mechanism by which the molecular variant M235T of the AGT gene is related to hypertension is poorly understood." (PMID 15811183, 2005). "Despite the large sample size, the present study fails to revise the odds ratio in a meta-analysis of a total of 25 studies on the association between the AGT M235T polymorphisms and hypertension in caucasians." (PMID 15642127, 2005). "The present study investigates the relationship between variants of the I/D ACE gene and M235T AGT gene, and the presence and severity of essential hypertension in a large homogeneous German population." (PMID 15642127, 2005). "In this study, the T235 variant of the AGT gene is associated with essential hypertension in Malaysian subjects." (PMID 15811183, 2005). "This case-control study was designed not only to determine the association of the AGT M235T gene variants with essential hypertension, but also its relationship to Plasma Renin Activity (PRA) in subjects attending the Health Clinic, Kuala Lumpur, Malaysia." (PMID 15811183, 2005). "In this study, it was found that the M235T polymorphism of the AGT gene is associated with essential hypertension." (PMID 15811183, 2005). "The data from this study suggest that the M235T polymorphism of AGT gene has a weak role in the manifestation of hypertension." (PMID 11434422, 2001). "In conclusion, there was a weak correlation between the M235T polymorphism of the AGT gene and hypertension in a retrospective cohort study corrected for various factors in Japanese subjects performed between 1992 and 1998." (PMID 11434422, 2001). "However, there was a strong correlation between hypertension and the T allele of M235T, which was linked to higher plasma AGT levels." (PMID 40640196, 2025). "Convincing evidence that the fourfold increase in the catalytic efficiency of cleavage of oxidised angiotensinogen is a sufficient cause for pre-eclamptic hypertension comes from Inoue and colleagues’ study of their index case of a 17-year-old with pre-eclampsia." (PMID 40699774, 2025). "In addition, TNF-α can cause hypertension via stimulating the production of endothelin 1 and angiotensinogen." (PMID 38275420, 2024). "Lead-related hypertension may also be associated with genes such as the M allele in the AGT gene and G allele carriers in the EDN1 gene." (PMID 39771076, 2024). "Understanding the pharmacogenetic implications of the AGT M235T variant may help in the personalized medicine approaches in hypertension management." (PMID 38541014, 2024). "Therefore, this case–control study aimed to investigate the association between AGT SNPs (rs2004776, rs3789678, rs5051 and rs7079) with hypertension in a study population of isiXhosa-speaking participants from the Eastern Cape Province in South Africa." (PMID 38706806, 2024). "This research aims to find out whether the AGT M235T polymorphism can be served as a genetic biomarker for the development of essential hypertension among individuals in Jordan." (PMID 38541014, 2024). "This inter-ethnic variation in the frequency of the AGT M235T genotype may explain, at least partly, the inter-ethnic variation in the predisposition to the diseases, including essential hypertension." (PMID 38541014, 2024).
Hypertension (continued). "AGT: Polymorphisms in the Angiotensinogen (AGT) gene, responsible for encoding a precursor of the vasoconstrictor angiotensin II, are associated with a predisposition to hypertension." (PMID 37965396, 2023). "For example, rs5051 in AGT is found to be associated with blood pressure lowering to beta-blockers in 115 Swedish patients with hypertension and left ventricular hypertrophy but with blood pressure lowering to ACEIs in 640 Chinese patients with essential hypertension." (PMID 36950018, 2023). "Recent studies have shown an association between AGT T174M (rs4762) polymorphism and hypertension." (PMID 37693342, 2023). "Among Europeans and Japanese, AGT variant (C4072T) was associated with hypertension." (PMID 36329155, 2023). "Moreover, the T174M polymorphism in the AGT gene had been identified as a risk factor for hypertension." (PMID 36845669, 2023). "Through a sibship analysis, it is shown that AGT variants are associated with hypertension, and plasma concentrations of angiotensinogen were significantly different among hypertensive subjects with different AGT genotypes providing a possible mechanism for the genetic links." (PMID 37201134, 2023). "Angiotensinogen deficiency in adipocytes of mice attenuated obesity-related hypertension." (PMID 37350982, 2023). "Many genetic variants of AGT have shown a positive association with hypertension." (PMID 36557328, 2022). "AGT regulates blood pressure; therefore, modifications to its gene sequence are expected to be crucial in the development of cardiovascular risk features including hypertension and the appearance of coronary artery disease (CAD)." (PMID 36557328, 2022). "The results obtained in the present study demonstrated that immunosuppression by MMF attenuates intrarenal AGT augmentation in Ang II-dependent hypertension, which is associated with mitigation of proteinuria, mesangial expansion and renal tubulointerstitial fibrosis." (PMID 35887028, 2022). "For the G(-6)A AGT gene polymorphism, the association under the codominant, dominant, and overdominant models was significant after adjustment for covariates (age, sex, BMI, smoking, diabetes mellitus, and hypertension)." (PMID 35886041, 2022). "For the A(-6)G AGT gene polymorphism, the association under the codominant, dominant, and overdominant models was significant after adjustment for covariates (age, sex, BMI, smoking, diabetes mellitus, and hypertension)." (PMID 35886041, 2022). "Importantly MMF did not attenuate the development of glomerular fibrosis in Ang II-dependent hypertension, suggesting that glomerular fibrosis is caused by pathological factors other than elevated IL-6 and augmented renal AGT." (PMID 35887028, 2022). "Finally, obesity is associated with increased adipose tissue renin and angiotensinogen, resulting in sodium retention and hypertension via activation of the renin--angiotensin system and the sympathetic nervous system." (PMID 35565750, 2022). "Thus, it indicates that angiotensin is an important factor mediating the hypertensive effect of erythropoietin and polymorphism of the angiotensinogen gene has a bearing on the development of hypertension." (PMID 33628672, 2021). "Interestingly, the T allele of M235T, which is related to higher plasma AGT, is well-associated with hypertension in Africans and Asians, such as Nigerian, Egyptian, Malaysian, and Japanese populations, but this association remains controversial in Caucasians." (PMID 33681303, 2021). "A polymorphism within the human angiotensinogen gene, resulting in an amino acid substitution at position 235 (M235T), has been shown to be significantly associated with both increased plasma angiotensinogen levels and hypertension." (PMID 34424335, 2021). "The association of obesity with hypertension might be due to adipocytes in obese individuals leading to the activation of the angiotensinogen which again increases sodium reabsorption and volume overload in the renal system." (PMID 34424924, 2021).
Hypertension (continued). "In addition, other AGT gene polymorphisms have been shown to be linked to hypertension, including G217A (substitution of guanine by adenosine at codon 217) and A20C (substitution of adenosine by cytosine at codon 20)." (PMID 34834033, 2021). "We now provide pathophysiological evidence that the conversion of the reduced form of AGT to its more active oxidized form is associated with inadequate antioxidant status and could indeed contribute to the hypertension of pre-eclampsia." (PMID 32029819, 2020). "Nevertheless, analysis of a very large UK Biobank that was recently made available revealed an association between polymorphisms in RAAS genes and hypertension-related traits at the significant threshold level of 5 × 10−8, e.g., rs699 in AGT with both SBP and DBP and rs4308 in ACE with DBP." (PMID 31511791, 2019). "Therapeutic inhibition of AGT mRNA expression using antisense oligonucleotides (ASOs) obviates developmental issues caused by genetic manipulations of AGT, thereby providing opportunities to more precisely determine roles of AGT in hypertension and many other diseases." (PMID 30530571, 2019). "Mutation in WNK1 and WNK4 genes could cause disturbances in the homeostasis of K+, salts, and pH level, whereas a mutation in AGT genes present on chromosome 1 results in an imbalance of angiotensinogen production, ultimately leading to hypertension." (PMID 30875817, 2019). "This could imply that a very large sample size might be required to have an adequate statistical power to detect association in hypertension-related traits, such as shown in AGT and ACE genes." (PMID 31511791, 2019). "Therefore, our study reestablishes the place of AGT as a risk gene for hypertension also in Indian populations." (PMID 28361007, 2017). "Based on the foundation laid by earlier studies, the present study hypothesized that the AGT genotype and haplotype will also associate with hypertension in Indian population." (PMID 28361007, 2017). "Significant associations observed for the leptin receptor (LEPR) gene and angiotensinogen (AGT) gene polymorphisms with obesity and hypertension, respectively, supported the notion that the prevalence of high-risk alleles increased with adaptation to an island environment." (PMID 28253292, 2017). "AGT gene variants were shown to be associated with hypertension." (PMID 27586550, 2016). "Genetic variations in AGT gene modify the plasma concentration of AGT and may be implicated in the pathogenesis of hypertension, coronary heart disease, and myocardial infarction." (PMID 27586550, 2016). "However, in multivariate analysis, the association between urinary AGT/Cr and eGFR was disappeared after adjustment with other clinical variables including age, gender, hypertension, and initial eGFR." (PMID 26092580, 2015). "Oxidized angiotensinogen may more readily predispose to hypertension associated with pre-eclampsia in view of the finding that this form releases angiotensin with greater efficiency at the cellular level than the free thiol, reduced form of angiotensinogen." (PMID 26312482, 2015). "Genetic and experimental models, such as mice which express human renin and angiotensinogen, renovascular hypertension (e.g., 2-kidney, 1-clip) and infusion of exogenous Ang II, are commonly used approaches to model human hypertension associated with increases in Ang II." (PMID 25400581, 2014). "By virtue of the function of AGT in regulating blood pressure, changes in its gene sequence are likely to play an important role in the pathogenesis of cardiovascular risk traits, such as hypertension, as well as manifestation of coronary artery disease (CAD)." (PMID 23497386, 2013). "One potential mechanism that may account for susceptibility to high blood pressure in obese neonates may involve increased production of angiotensinogen (AGT), a source for angiotensin (Ang) II." (PMID 23251800, 2012).